HLA-G (major histocompatibility complex, class I, G)
Diseases named in the same sentence as HLA-G in open-access papers (continued):
Sharing a sentence is not in itself a finding about the gene and the disease.
Miscarriage (14 papers, 2016 to 2025). A pregnancy that ends at a stage in which the fetus is incapable of surviving on its own, defined as the spontaneous loss of a fetus before the 22th week of pregnancy. "A miscarriage or unsuccessful implantation may arise from an immune-mediated assault on the embryo caused by low HLA-G expression." (PMID 39165943, 2024). "Moreover, a study performed by our group on the KIR, LILRB1 and HLA-G association with spontaneous miscarriage indicated that polymorphism of partners in KIR2DL4 could be associated with susceptibility to miscarriage of their women." (PMID 28523429, 2017). "The great interest in HLA-G is due to its potential use as a clinical marker for adverse pregnancy outcomes, including miscarriage, RPL and recurrent implantation failure (RIF)." (PMID 36768880, 2023). "s-HLAG plasma concentration during pregnancy seems to be a more promising tool as a miscarriage marker in women with RPL." (PMID 36768880, 2023). "Multivariate analysis indicated that women’s −716 HLA-G and LILRB1 and men’s KIR2DL4 9A/10A are important in terms of the protection or susceptibility to miscarriage, respectively (p = 0.00968)." (PMID 26973020, 2016). "Measuring immunomodulatory factors such as HLA‐G, TGF‐β and IL‐6 may help identify male partners whose seminal immune environment is associated with suboptimal implantation or higher miscarriage risk." (PMID 41395839, 2025). "HLA-G -725C>G polymorphism located at the 5’upstream regulator region (5’URR) or promoter region is reported to change the methylation profile of CpG dinucleotide, resulting in a modification of HLA-G expression and also linked to miscarriage." (PMID 36532068, 2022). "However, HLA-G expression levels can be altered by disorders of reproduction; for example, lower HLA-G expression levels were found in women with early pregnancy failure, such as miscarriage and recurrent abortion." (PMID 36538164, 2023). "This suggest the HLA-G*01:01/UTR-4 could be a protection against inflammatory conditions and pathological states, not just found in women with secondary recurrent miscarriage, but also in CKD patients." (PMID 30794652, 2019).
Autoimmunity (13 papers, 2014 to 2025). The occurrence of an immune reaction against the organism's own cells or tissues. "Although it shows a restricted tissue expression pattern, with a relevant role in the maintenance of fetal–maternal immune tolerance, HLA-G expression has been associated with different diseases, particularly autoimmunity and cancer." (PMID 36233078, 2022). "In conclusion, the collected data confirmed the association with the immunosuppressive activity of HLA-G antigens (particularly the HLA-G-5 isoform), HLA-G-positive Treg lymphocytes and autoimmunity remission in MS." (PMID 34948145, 2021). "The first one concerns the role of HLA-G in presenting endogenous antigens (derived from viruses or bacteria present in the intestine) that trigger the development of the autoimmunity through molecular mimicry." (PMID 34948145, 2021). "However, HLA-G expression has also been reported in some pathological conditions, such as cancer and autoimmunity." (PMID 35154112, 2022). "On the other hand, since Dan Geraghty and Edgardo Carosella groups uncovered HLA-G structure and immune system modulation by this molecule, another flood of HLA-G and disease studies has occurred, particularly in relation to autoimmunity, cancer, and fetal/maternal pathologies." (PMID 35925520, 2022). "Finally, multiple regression analysis, considering DC-10 and HLA-G-related parameters, showed that Abneg FDRs are more similar to subjects with autoimmunity than to HCs." (PMID 34659254, 2021). "Genes coding for class I and II major histocompatibility molecules (MHC) were also found in the group 2 network, highlighting the role of HLA-G (MHC class I) for protecting renal transplants from autoimmunity and the function of Hla-dpb1 (MHC class II) in renal allograft rejection." (PMID 26742487, 2016). "For example, it is interesting to note that inflammatory cutaneous diseases present a disproportional expression of HLA-G molecules with respect to controls and that this could generate autoimmunity." (PMID 25477881, 2014). "Overall, these data sustain anti-inflammatory properties of sHLA-G molecules, and in particular HLA-G-5 isoform, which could lead to the remission of MS autoimmunity." (PMID 25477881, 2014). "Thus it appears that down/over-expression of HLA-G may not only act as an immunosuppressive and beneficial molecule but may also sustain an unbalanced immune stimulation and autoimmunity." (PMID 25477881, 2014). "Although several studies have examined the role of HLA-G in autoimmunity, no previous work has specifically investigated the genetic and molecular profile of HLA-G in PBC." (PMID 40799641, 2025). "Moreover, the high frequency of HLA-G UTR-3, previously shown to be associated with HLA-G expression levels, in individuals at risk to develop T1D without signs of autoimmunity (Abneg FDRs) could represent a protective factor toward the disease development." (PMID 34659254, 2021). "The dependency between the percentage of HLA-G+ DC-10 and the percentage of CD83+ DC-10 was also detected in HCs (p = 0.0069) but not in Abpos FDRs or T1D patients (subjects with autoimmunity)." (PMID 34659254, 2021).
hepatocellular carcinoma (13 papers, 2015 to 2024). A malignant tumor that arises from hepatocytes. "Tumour HLA-G expression correlated with poor clinical outcome in breast, esophageal, gastric and hepatocellular carcinoma patients." (PMID 34361031, 2021). "miR-133a, which controls HLA-G protein stability, is decreased in ovarian, prostate, and bladder cancer, whereas miR-148/152, which also regulate HLA-G, are downregulated in hepatocellular carcinoma and gastrointestinal cancers." (PMID 29403493, 2018). "This study was undertaken to determine genetic variations at the 3’-UTR of the HLA-G gene that may alter its expression, identify risk alleles and genotypes for their association with hepatocellular carcinoma (HCC), and treatment responses in the Indian population." (PMID 39703498, 2024). "Both HLA-G mRNA and protein expression have been reported in hepatoma cell lines." (PMID 39703498, 2024). "In addition, Chinese patients exhibiting the 14-bpDEL/DEL genotype presented increased HLA-G expression in hepatocellular carcinoma specimens." (PMID 25699038, 2015).
endometrial cancer (11 papers, 2014 to 2025). Primary or metastatic malignant neoplasm involving the endometrium (mucous membrane that lines the endometrial cavity). "In endometrial cancer, researchers have also found upregulation of HLA-G expression, and the increased soluble HLA-G levels are associated with advanced pathological staging, metastasis, and poor prognosis in endometrial cancer patients." (PMID 38818502, 2024). "Endometrial epithelia cells are antigen-presenting cells that express major histocompatibility complex (MHC) and non-classical MHC class I molecules and human leukocyte antigen G (HLA-G) is down regulated in endometrial cancer." (PMID 30813939, 2019). "Nonetheless, no survival-related factors were associated with tumour HLA-G expression in endometrial carcinoma patients." (PMID 34361031, 2021). "They concluded that HLA-G may serve as a clinical marker for the preoperative prediction of metastatic endometrial cancer." (PMID 24870375, 2014). "The expression of HLA-G and IDO has been detected in endometrial cancer, with an increased expression of the two molecules in tumors as compared to surrounding normal tissue." (PMID 35328349, 2022). "Inconsistent with the present results, the findings of previous studies showed that high expression levels of HLA-G were an independent marker of poor prognosis in some tumors, including NSCLC, ovarian, breast, colorectal, hepatocellular and endometrial cancers." (PMID 34276642, 2021). "However, there is currently no research definitively stating whether HLA-G is involved in the pathogenesis and progression mechanisms of hypothyroidism and endometrial cancer." (PMID 38818502, 2024). "Thus, IDO and HLA-G immunosuppressive functions in endometrial cancer are not directly related." (PMID 35328349, 2022).
pancreatic cancer (11 papers, 2011 to 2024). "Four studies investigated the association between tumour HLA-G expression and clinical outcome of pancreatic carcinoma patients." (PMID 34361031, 2021). "Therefore, further research on the association between HLA-G expression and clinical outcome of pancreatic carcinoma patients is warranted." (PMID 34361031, 2021). "Thus, there is no apparent link between the percentage of HLA-G-positive tumour samples and the subsequent verdict on the association between HLA-G expression and clinical outcome of pancreatic carcinoma patients." (PMID 34361031, 2021). "Thus, considerable contradictions were observed concerning the association between HLA-G expression and clinical outcome of pancreatic carcinoma patients between different studies." (PMID 34361031, 2021). "In fact, plasma levels of soluble HLA-G are higher in patients with pancreatic cancer compared to healthy donors, and soluble HLA-G levels inversely correlate with the number of peripheral activated T cells." (PMID 30574154, 2018). "They analyzed HLA-G expression in a cohort of patients with pancreatic carcinoma and found high levels of HLA-G in the majority of tumor samples." (PMID 27652273, 2016). "Cervical, colorectal, lung, oral, ovarian and pancreatic carcinoma patients did not univocally reveal poor clinical outcome associated with HLA-G expression." (PMID 34361031, 2021). "The resistance of MICA/B-positive pancreatic cancer to NK-92 cell killing could be due to the inhibitory effect of co-expressed HLA-G antigen that suppresses NK cell function." (PMID 21605422, 2011). "Consistent with the present results, the findings of previous studies showed that high expression levels of HLA-G were related to better OS and DFS in rectal cancer patients but worse OS in pancreatic carcinoma patients." (PMID 34276642, 2021). "In pancreatic cancer HLA-G is a negative prognostic marker, and downregulation of ILT-2 (the receptor of HLA-G) in immune cells activates anti-tumor immunity." (PMID 30930892, 2019). "Based on the current information, breast, gastric, hepatocellular and esophageal carcinoma might qualify for ICI HLA-G therapy, while cervical, colorectal, lung, oral, ovarian and pancreatic carcinoma still does not." (PMID 34361031, 2021). "Until then, no conclusive verdict can be given on the role of HLA-G in pancreatic carcinoma." (PMID 34361031, 2021).
abortion (10 papers, 2012 to 2024). the ending of pregnancy by removing a fetus or embryo before it can survive outside the uterus. "In our case–control study, we tried to elucidate an association of particular genetic variants of KIR2DL4, LILRB1 and its ligand HLA-G in women as well as in their partners with susceptibility to spontaneous abortion." (PMID 26973020, 2016). "Several studies show that specific types of HLA-G alleles are associated with increased risk of recurrent spontaneous abortion." (PMID 25469137, 2014). "Abnormal reduction of HLA-G expression level (either soluble or membrane-bound form) in the early months of pregnancy may lead to an increased risk of immunologic response of the mother immune system against the fetus, resulting in abortion." (PMID 25469137, 2014). "The presence of soluble HLA-G in human embryo culture supernatants after in vitro fertilization (IVF) correlates with successful pregnancy and reduced levels of HLA-G in maternal circulation has been reported in disorders of pregnancy, such as pre-eclampsia and recurrent spontaneous abortion." (PMID 22934097, 2012). "We found a protective effect of women’s heterozygosity in −716 HLA-G (p = 0.0206) and LILRB1 (p = 0.0131) against spontaneous abortion." (PMID 26973020, 2016).
clear cell renal cell carcinoma (10 papers, 2015 to 2024). "A recent study focused on tumour-infiltrating CD8+ T cells that express the HLA-G receptor ILT2 in clear cell renal cell carcinoma (ccRCC), and the results emphasize the potential of therapeutically targeting the HLA-G/ILT2 checkpoint in HLA-G+ tumors." (PMID 34276642, 2021). "In particular, HLA-G has been shown to be up-regulated in 50 % of clear cell renal cell carcinomas and the presence of its soluble form has been detected in plasma of these patients." (PMID 26704308, 2015). "Furthermore, novel alternatively spliced HLA-G isoforms have been characterized in clear cell renal cell carcinoma specimens, which may theoretically also occur in colon cancers and influence the staining patterns." (PMID 35027037, 2022). "Human leukocyte antigen G (HLA‐G), a recently identified immune checkpoint, has been detected in many types of primary tumors and metastases, in malignant effusions as well as on tumor‐infiltrating cells, particularly in patients with clear cell renal cell carcinoma (ccRCC)." (PMID 28815885, 2017). "HLA-G/ILT-4 signaling was crucial to tumor angiogenesis, documented with that the interplay between HLA-G and ILT4 boosted the expression of VEGF-C in clear cell renal cell carcinoma and NSCLC, thereby facilitating the tumor growth and lymphatic metastasis." (PMID 38310272, 2024). "In clear-cell renal-cell carcinoma (ccRCC), LILRB1+ TIL CD8 T cells exhibit reduced cytotoxicity in the presence of HLA-G-expressing target cells, which can be reversed by anti-HLA-G-mediated blockade." (PMID 38785789, 2024).
HCMV infection (10 papers, 2014 to 2025). "Next, given the role of HLA-G during CMV infection, the HLA-G del/del polymorphism was assessed in relation to CMV viral load." (PMID 29354123, 2017). "In order to explore the possible role of HLA-G molecules in congenital HCMV infection, we analyzed maternal and fetal sHLA-G and b2M expression in correlation with the risk of transmission and severity of HCMV infection." (PMID 27699182, 2016). "In this work we investigated the expression of soluble (s)HLA-G and beta-2 microglobulin (component of HLA) molecules in correlation with the risk of transmission and severity of congenital HCMV infection." (PMID 27699182, 2016). "The HLA-G 14 bp insertion/deletion polymorphism is also a putative susceptibility factor for active hCMV infection in children." (PMID 24839609, 2014). "Interestingly, a polymorphism in the 3′-untranslated region of the HLA-G gene that affects HLA-G expression levels has been reported to modify susceptibility to CMV infection." (PMID 30386347, 2018). "Interestingly, this HLA-G del/del polymorphism has been associated with active CMV infection with higher viral loads in children." (PMID 29354123, 2017). "Membrane-bound HLA-G was shown to be expressed in macrophages and monocytes undergoing lytic infection, while sHLA-G levels are increased in serum of patients with acute HCMV infection." (PMID 35237271, 2022). "The VMAPRTLFL UL40 derived peptide mimics the signal peptide of HLA-G, the expression of which is upregulated during inflammation, HCMV infection and HIV-1 infection, and specifically enhances antibody-driven adaptive NK cell responses as recently described." (PMID 32132995, 2020). "Co-expression of HCMV gene products and HLA-G has been demonstrated for macrophages with reactivated CMV infection on a single-cell level." (PMID 30386347, 2018). "Macrophages and monocytes express HLA-E and de novo induction of monocyte HLA-G cell surface expression was reported for active HCMV infection and reactivation of latent infection in vitro." (PMID 30386347, 2018). "HCMV infection modifies HLA-G expression in tissues and immune cells, with a downmodulation in infected cytotrophoblasts and upregulation in infected peripheral blood cells." (PMID 27699182, 2016). "To explore HCMV antigen presentation by HLA‐G, we anticipated the need of a cell line permissive for HCMV infection, selectively expressing the class Ib molecule to allow its purification by affinity chromatography with the available W6/32 mAb specific for HLA‐I molecules." (PMID 40347012, 2025). "The single nucleotide polymorphism (SNP) (3142C>G) in the HLA-G gene of the recipient, but not in the transplant donor was associated with a higher susceptibility to HCMV infection after kidney transplantation." (PMID 35237271, 2022). "Together with recent studies, that show the profound impact of the HLA-G-derived leader peptide, we are tempted to speculate that only CMV infection provides both, elevated HLA-E and HLA-G expression on a single cell level." (PMID 30386347, 2018). "Both membrane-bound and soluble plasma HLA-G concentrations increase during hCMV infection." (PMID 24839609, 2014). "According to our results, a similar role for HLA‐G appears unlikely, though the possibility that priming by viral antigens might occur in the inflammatory context associated with HCMV infection of HLA‐G+ EVT is not ruled out." (PMID 40347012, 2025). "Apparently, the presence of hCMV infection, which generates different HLA-E-stabilizing peptides, induces the formation of hCMV-specific NK cells, the response of which is accelerated then by the presentation of the LFL peptide derived from HLA-G." (PMID 38534374, 2024). "Both membrane bound and soluble levels of HLA-G are reported to be increased in untreated HIV-1 infection and during HCMV infection and have been shown to correlate with blood IFN-γ concentrations and could therefore represent a source of HLA-E peptides in T/T individuals." (PMID 32132995, 2020).
HCMV infection (continued). "Despite the significant enrichment of HLA-G positive EVTs under differentiated conditions, we found that there was no significant enhancement of HCMV infection under these conditions, suggesting that EVTs are not the primary targets of HCMV infection in TOs." (PMID 35975985, 2022).